PAX7 (paired box 7)
Diseases named in the same sentence as PAX7 in open-access papers (continued):
Sharing a sentence is not in itself a finding about the gene and the disease.
tumor (continued). "Evidence for impaired myogenesis was noted in the tumor-bearing mice as evidenced by increased levels of Pax7." (PMID 24877061, 2014). "Even if the number of samples was low for each subset, a statistical analysis showed a significant P value between (Pax3+) and (Pax7+) and between (Pax+) and (Pax−) tumours, 0.05 and 0.0005 respectively." (PMID 21437224, 2011). "Alveolar tumours typically harbour one of the two characterised chromosomal translocations that juxtapose PAX gene family member PAX3 or PAX7 with the Forkhead-related FKHR (FOXO1A) gene." (PMID 12865925, 2003). "Here, we have quantified the relative levels of chimaeric and wild-type PAX transcripts in various subtypes of RMS (n=34) in order to assess the relevance of wild-type PAX3 and PAX7 gene expression in these tumours." (PMID 12865925, 2003). "Tumours of the alveolar subtype frequently harbour one of two characteristic translocations that juxtapose PAX3 or PAX7, and the forkhead-related gene FKHR (FOXO1A)." (PMID 12865925, 2003). "This suggests that PAX7 may promote tumor proliferation by dysregulating cell cycle checkpoints, providing a mechanistic link to its prognostic significance." (PMID 41532150, 2026). "In contrast, our previous analysis of Myf5 and Pax7 expression in these tumours indicated that the expression status of these myogenic markers did not reflect the cell of origin; this finding suggests that expression phenotype is not fully synonymous with cellular origin." (PMID 39812007, 2025). "In contrast, RMS tumours in which a Pax3::Foxo1 fusion is directed to the Pax7 lineage do not demonstrate differing methylation from RMS tumours in which other mutations are directed to the Pax7 lineage." (PMID 39812007, 2025). "Our analysis yielded a total of 153 DM/DE genes between Myf5 lineage and Pax7 lineage tumours." (PMID 39812007, 2025). "While the primary focus has been on proliferation, there is also evidence suggesting that PAX7 may influence tumour cell invasion and migration." (PMID 40370330, 2025). "Moreover, the multi-kinase inhibitor sorafenib has demonstrated the ability to modulate STAT3 activity, preventing the accumulation of atrogin-1 and Pax7 in skeletal muscle, thereby improving functional capacity and reducing fatigue in tumor-bearing animals." (PMID 40704145, 2025). "In FN‐RMS cells, reducing PAX7 expression results in tumours that are less invasive and have different histological features, indicating that PAX7 may be involved in maintaining the invasive properties of these cells." (PMID 40370330, 2025). "Finally, tumours in MR2 corresponded to either Pax3::Foxo1 in the Pax7 lineage or DNA alterations other than Pax3::Foxo1 in one of three lineages (Myf6, Pax3, or Pax7)." (PMID 39812007, 2025). "However, developing PAX7::FOXO1 tumor models would allow for comparative analyses to identify mechanisms responsible for disease aggressiveness." (PMID 38916046, 2024). "MYCi361-treated tumor cells also showed decreased expression of the stem genes pax7 and myf5." (PMID 37345125, 2023). "WFA treatment in tumor-bearing and naïve mice led to a robust increase in the proportion of differentiating satellite cells (i.e., Pax7+/MyoD+), whereas the vehicle-treated groups had an overwhelming majority of satellite cells that were quiescent or returning to quiescence (i.e., Pax7+/MyoD–)." (PMID 33718372, 2021). "PAX7 knockdown significantly reduced tumor volume and mass in SMS-CTR cell xenografted mice." (PMID 34535684, 2021). "Consistently, eRMSs express markers of quiescent or activated satellite cells such as Pax7, MyoD and Myog that could contribute to tumor development." (PMID 33671425, 2021). "Furthermore, proteins in the myogenesis (Pax7/MyoD/MyoG) and myofiber survival (Dock3/Pten/Akt) networks, which are regulated by and/or regulate miR-486, are deregulated in skeletal muscles of tumor-bearing transgenic mice compared to controls." (PMID 31941005, 2020).
tumor (continued). "Pax7 is a positive regulator of satellite cell proliferation, which has been reported to be disrupted in cachectic muscle from mice and cancer patients; dysregulation of Pax7 in cachectic muscle was driven by aberrant NF-κΒ signaling induced by circulating tumor derived factors." (PMID 32982782, 2020). "Moreover, PAX7 overexpression in hindlimb muscles is sufficient to induce atrophy, while tumor-bearing Pax7+/− mice display less muscle atrophy than Pax7+/+ ones." (PMID 32824440, 2020). "In tumor-bearing mice that recapitulated clinical features of cancer-induced cachexia, as well as in muscle biopsies from patients with pancreatic cancer, a significant expansion of cells expressing high levels of the SC-marker Pax7 was observed." (PMID 26257645, 2015). "Interestingly, U29415 tumor cells of Pax7CreER satellite cell lineage showed a paradoxical increase in mRNA levels of Pax7 and Pax3:Foxo1 when treated with 20 μM 5-Aza-2′deoxycytidine, 15 μM entinostat, and 5 μM SAHA." (PMID 25030697, 2014). "Yet to be identified factors present in the serum of tumor-bearing mice are responsible for Pax7 upregulation and block of myogenic potential in muscle stem cells, a capacity not fully recapitulated by administration of specific, albeit important, recombinant cytokines, such as TNF-alpha." (PMID 24877061, 2014). "PAX3-and PAX7-FKHR gene fusion, mutations in the von Hippel Lindau gene, hypoxic conditions in the tumor microenvironment, NF-κB, vascular endothelial growth factor, and tumor necrosis factor alpha have all been found to regulate CXCR4 overexpression in different tumor cells." (PMID 23472074, 2013). "PAX3- and PAX7-FKHR gene fusion, mutations in the von Hippel Lindau tumor suppressor gene, hypoxia in the tumor microenvironment, NF-κB, and inflammatory cytokines such as vascular endothelial growth factor and tumor necrosis factor alpha, have all been implicated in CXCR4 overexpression." (PMID 21880153, 2011). "These tumours are thought to originate from a multipotential mesenchymal cell type and are correlated with translocations between chromosomes 1 or 2 and chromosome 13, resulting in the generation of Pax3- or Pax7- forkhead (Pax3-7/FKHR) chimaeric genes." (PMID 18289368, 2008). "Furthermore, as myogenic satellite cells are known to express PAX7, this pattern of PAX7 expression suggests this cell type as the origin of these tumours." (PMID 12865925, 2003). "Therefore, simultaneous Pten and Pax7 loss in murine FN-RMS not only rescued the effects of Pten loss in these tumors but identified a synthetic essential relationship between Pten and Pax7 controlling tumor cell fate." (PMID 34535684, 2021). "Moreover, by comparative analysis within each tumor cell culture, of CD15high and CD15low subpopulations, it was reported that CD15high cells are also associated to higher SOX2 and PAX7 expression, and were detected in higher percentage in recurrent PAs as compared to the matched primary tumor." (PMID 32153500, 2020). "Consistently, alcohol reduced the expression of paired box 7 (Pax7) in GA muscle of tumor mice, indicating decreased satellite cell density; mRNA expression of myogenin (MyoG) was down-regulated in both control and tumor mice, suggesting impaired myogenesis and muscle protein synthesis." (PMID 29245988, 2017). "Moreover, a detailed examination of events within muscles from tumor-bearing mice revealed that the induction of NF-κB activity by cachectic serum contributed to Pax7 dysregulation in muscle-resident progenitors, and was followed by a significant decline in muscle mass." (PMID 26257645, 2015). "Indeed, the activation of the Polycomb Repressive Complex 2 (PRC2) by p38α kinase results in the formation of repressive chromatin on the Pax7 locus, thereby providing an additional interventional target that could be explored in a tumor-promoting milieu." (PMID 26257645, 2015).
tumor (continued). "Immune infiltration analysis revealed a significant correlation between PAX7 and the infiltration levels of Th2 cells, TReg, and TFH within the tumor microenvironment." (PMID 41532150, 2026). "In both tumor-free and tumor-bearing mice treated with WFA, we observed a significant increase in Pax7 levels and a notable rise in Myod1 expression compared to the vehicle-treated groups." (PMID 39996717, 2025). "Dependence on PAX7 was evident in both cell line models of RMS and patient‐derived xenografts (PDX), where PAX7 knockdown resulted in significantly reduced tumour growth and viability." (PMID 40370330, 2025). "Taken together, these evidences confirm that these HEMTIRGs (CRISP3, PAX7, FGG, and DCD) are closely related to hypoxia, EMT, and tumor immunity, which in turn contribute to the regulation of BC pathogenesis and prognosis." (PMID 41200166, 2025). "For tumor size, tumor invasiveness (T1 vs. T2) and FOXO1 fusion partner (PAX3 vs. PAX7) a significant correlation was observed for OS." (PMID 39781573, 2025). "MYC bound to the promoter containing the consensus MYC binding motif (CACGTG) of YBX1, CD133 and muscle satellite/RMS tumor propagating cell markers MYF5 and PAX7." (PMID 37345125, 2023). "Within the tumor-free groups, WFA treatment significantly increased the normalized amount of Pax7+ cells (WFA 2 mg/kg: 0.28 ± 0.02; WFA 4 mg/kg: 0.42 ± 0.01) compared to the tumor-free vehicle-treated group (0.06 ± 0.01) (p < 0.0001 for both comparisons)." (PMID 33718372, 2021). "Compared to normal samples, the expression of E2F2, FOXJ1, EMX1, PAX7, NKX6-1, FOXD1, and ZNF552 was significantly higher (P < 0.05) and the expression of MSX1, STAT4, NR3C2, and EGR3 was significantly lower in tumor samples (all P < 0.05)." (PMID 33688372, 2021). "The expression of PAX7 and RUNX3 were similar between ES cell lines and were significantly higher in RD-ES cell line in comparison to other tumor cell lines (p < 0.01)." (PMID 33924679, 2021). "To conclude, our results suggest that tumor cell lines with the same STR profile can produce subclones that differ in many features and indicate crucial roles of PAX7 and ID proteins in the development of RMS." (PMID 34440639, 2021). "Genetic deletion of miR-206 in a mouse model of FN-RMS accelerated and exacerbated tumor development, indicating that both in vitro and in vivo miR-206 acts as a tumor suppressor in FN-RMS at least partially through downregulation of PAX7." (PMID 27277678, 2016). "In ERMS, high expression of PAX7 upregulates EPHA3 and EFNA1 to promote migration and invasiveness of tumor cells." (PMID 26636678, 2015). "Here we show greatly elevated levels of PAX7 expression in a large cohort of primary ERMS tumours, and generally lower, less frequent expression of PAX7 in primary RMS tumours with PAX-FKHR fusion genes." (PMID 12865925, 2003). "In histopathological analysis, the tumours resembled human ERMS, expressing low Pax3 levels, and elevated Pax7 levels, which generally mirrored c-Met expression." (PMID 12865925, 2003). "As expected, expression of the fusion genes was restricted to tumours known to harbour the relevant translocation, with relative expression levels of PAX3-FKHR varying between 0.3- and 3.1-fold and those for PAX7-FKHR between 0.8- and 2.1-fold." (PMID 12865925, 2003). "Expression of each of the wild-type PAX3 and PAX7 genes and the two fusion genes PAX3-FKHR and PAX7-FKHR was measured by quantitative real-time PCR in 34 primary RMS tumours and in three RMS cell lines." (PMID 12865925, 2003). "Furthermore, immune response analysis revealed that the tumor infiltration of Th2 cells, TReg, and TFH was significantly higher in the PAX7‐highly expressed patients." (PMID 41532150, 2026). "Previous work has shown that in limb muscles of cachectic mice‐bearing C26 tumours, PDGFRα is also expressed by Pax7+ cells of nonsatellite cell origin that accumulate in cachectic muscle, yet fail to differentiate." (PMID 39810606, 2025).
tumor (continued). "Based on the prevalence of Myf5 and Pax7 lineages in MR1 and MR2, respectively, we examined whether the Myf5 and Pax7 genes were DM between MR1 and MR2 tumours." (PMID 39812007, 2025). "Two distinct methylation‐defined subsets were found for GEMM RMS tumours with no/low Pax3::Foxo1 expression: one subset enriched in Pax7 lineage tumours and a second subset enriched in myogenic factor 5 (Myf5) lineage tumours." (PMID 39812007, 2025). "The tumor cells expressed CD99, synaptophysin, CD56, MUC4, and EMA (focal), but not AE1/AE3, S100, smooth muscle actin, desmin, CD34, chromogranin A, GFAP, NKX2-2, PAX7, and INSM1." (PMID 39249507, 2024). "Interestingly, PAX7 along with MYOD1 are the only genes that are both members of FN-RMS core-regulatory circuits and are FN-RMS dependencies thus coupling tumor cell identity and survival 34,35." (PMID 34535684, 2021). "Our results suggest that if PAX7 is present in PAX3-FOXO1 positive ARMS cells, downregulation of its level may force tumor to differentiate and inhibit its proliferation and progression." (PMID 34440639, 2021). "Interestingly, within the tumor-bearing groups, the WFA 2 mg/kg group displayed a significant reduction in Pax7+ cells (0.26 ± 0.01) compared to the vehicle-treated and WFA 4 mg/kg groups (0.31 ± 0.01) (p < 0.0001 for both comparisons)." (PMID 33718372, 2021). "In contrast, among surface markers downregulated in PAX7+ cells were CD15 (SSEA1), which may serve as a marker of tumor-propagating cells and sialophorin CD43 that mediates tumor cell-peritoneal adhesion." (PMID 34440639, 2021). "Following CTX injury, Pax7+ cells increased in both sham and LLC animals, with a 2-fold increase for sham control animals as compared to the uninjured leg and a 4.5-fold increase over the uninjured leg in tumor-bearing animals to almost 20% of nuclei." (PMID 26709824, 2015). "Expression levels were quantified relative to expression in the RD cell line (RDCL) for PAX3 and PAX7, the Rh30 cell line for PAX3-FKHR and a primary tumour (sample 6) for PAX7-FKHR, since no cell line expressing this fusion gene was available." (PMID 12865925, 2003). "As the MR2 subset contains Pax7 lineage tumours both with and without Pax3::Foxo1 knock‐in, these findings further reinforce the notion that the functional and epigenetic impact of Pax3::Foxo1 in the Pax7 lineage is very limited." (PMID 39812007, 2025). "We found lowered Pax7 mRNA abundance in males and females, regardless of leucine supplementation, corroborating prior findings of our laboratory, which show decreased Pax7 mRNA levels in tumor-bearing male and female LLC mice." (PMID 37960223, 2023). "In addition, we showed that in C26 tumor-bearing mice voluntary wheel running downregulates Pax7 expression to levels similar to those observed in not exercised healthy mice." (PMID 27034684, 2016). "Further, while injury did not affect the percentage of Pax7+/C/EBPβ+ satellite cells in healthy animals, in the tumor-bearing cohort, the percentage of double positive cells was increased in both uninjured and injured muscle, consistent with the ex vivo analysis of satellite cells." (PMID 26709824, 2015). "Since in the absence of TRIM32, Pax7+ muscle stem cells fail to differentiate, one may hypothesise that this lack of differentiation could lead to tumour formation." (PMID 22299041, 2012). "PAX7 expression is implicated in the specification and maintenance of satellite cells, and here we have shown that PAX7 expression is almost completely restricted to RMS tumours with no known translocation." (PMID 12865925, 2003). "However, we found, for the first time, that voluntary physical activity per se did not induce a significant increase in the expression of Pax7 and MyoD, albeit it specifically downregulated Pax7 expression in the musculature of tumor-bearing mice, likely releasing a block to muscle regeneration." (PMID 27034684, 2016).
tumor (continued). "This tumour was fusion negative, showing increased copy number (up to 10 per cell) for PAX3, PAX7 and FOXO1 and displaying TFAP2B positive reaction." (PMID 31493794, 2019). "By contrast, PAX7 mRNA expression corresponded to translocation status rather than histological subtype, with PAX7 expression detected in both ARMS and ERMS, but mainly restricted to tumours lacking either a PAX3-FKHR or a PAX7-FKHR fusion gene." (PMID 12865925, 2003). "These analyses revealed that the tumors lacked expression of any markers of muscle differentiation (PAX7, MYOD, MYOGENIN) but were positive for VIMENTIN, while some spindled and larger eosinophilic tumor cells expressed smooth muscle actin (SMA), suggestive of focal myofibroblastic differentiation." (PMID 33924486, 2021). "Furthermore, we extracted also literature data of PAX7 expression levels in 25 RMS cell lines and 90 tumor samples positive or negative for PAX3-FOXO1 and presented them in dot plot graphs." (PMID 34440639, 2021). "However, elevated PAX7 expression in ERMS is not accompanied by elevated PAX3 expression, suggesting that this tumour type is not derived from proliferating myoblasts in the dermomyotome." (PMID 12865925, 2003). "We used this technique to measure mRNA levels for wild-type PAX3, PAX7, PAX3-FKHR and PAX7-FKHR in RMS, to determine whether higher levels of wild-type PAX3 and PAX7 are observed in tumours that do not express PAX3-FKHR and PAX7-FKHR chimaeric transcripts." (PMID 12865925, 2003).